LDHA (lactate dehydrogenase A)
Diseases named in the same sentence as LDHA in open-access papers (continued):
Sharing a sentence is not in itself a finding about the gene and the disease.
cancer (continued). "LDHA plays a pivotal role in the synthesis of lactate, and it drives cancer cells’ preference for aerobic glycolysis in PDAC." (PMID 38711083, 2024). "The activation of LDHA has been considered a crucial step in cancer metabolic reprogramming, promoting cancer growth and progression." (PMID 38704368, 2024). "To further analyze the association between LDHA CNV and patient prognosis, we examined the number of patients with LDHA amplification or deletion in each cancer type." (PMID 38198170, 2024). "LDHA is involved in various stages of cancer, including tumorigenesis, development, progression, invasion, metastasis, angiogenesis, and immune escape." (PMID 38731521, 2024). "As a result, LDHA has emerged as a significant biomarker and a promising target for the diagnosis and treatment of a wide range of cancers." (PMID 39479443, 2024). "Lactate dehydrogenase (LDHA) catalyses the hydrogenation of pyruvate to produce lactic acid, and the lactic acid produced by glycolysis contributes to the progress of malignant tumours to a large extent." (PMID 38288377, 2024). "LDHA is an aerobic glycolysis-related key enzyme contributing to lactate production in cancer cells." (PMID 38443336, 2024). "Genomic alteration of LDHA was common in different types of cancer, while with prognostic value in pan-cancers." (PMID 38709280, 2024). "LDHA expression was significantly higher in cancer tissues than in the corresponding adjacent tissues, as observed by IHC (p < 0.0001)." (PMID 38993839, 2024). "The strategic targeting of LDHA presents a multifaceted approach to cancer treatment, offering both metabolic regulation and a means to induce cell death through oxidative stress." (PMID 39479443, 2024). "Among the cancer types, BRCA exhibited the highest number of LDHA CNV variants, with forty-nine patients showing LDHA amplification and twenty-nine patients displaying LDHA deletion." (PMID 38198170, 2024). "After that, we accessed the prognostic significance of LDHA expression in overall survival for pan-cancer in thirty-three cancer types." (PMID 38709280, 2024). "LDHA is overexpressed in different cancer cells and is considered a biomarker for multiple malignant tumors and is closely related to poor prognosis." (PMID 38764020, 2024). "Previous studies have reported that LDHA is highly expressed in aerobic glycolytic cancer lineages, suggesting that the up-regulation of LDHA can be induced in a hypoxic state." (PMID 38510704, 2024). "In summary, LDHA emerges as a plausible therapeutic target across diverse cancer types, and the other top-ranked genes are imperative for advancing the development of a comprehensive immunotherapeutic strategy." (PMID 38664705, 2024). "LDHA is thought to be the predominant form of LDH found in cancers and otherwise is primarily found in the liver and striated muscle." (PMID 39334961, 2024). "ATP appears to link the PI3K/AKT signaling pathway and LDHA in a feedback loop, playing an important role in cancer cells’ chemotherapy sensitivity to LBP." (PMID 39680520, 2024). "Studies on various cell lines have shown that inhibiting LDHA function leads to decreased cancer cell proliferation, increased apoptosis, and weakened migration and invasion, further confirming the importance of LDHA as a potential therapeutic target." (PMID 39877360, 2024). "Inhibition of LDHA activity effectively impairs the growth of tumors in various types of cancer cells." (PMID 38474453, 2024). "Scoring and grouping were performed using the intensity of LDHA protein staining in the cancer cells." (PMID 39343933, 2024). "The LDHA isoform is highly expressed due to its preference for catalyzing the conversion of pyruvate to lactate in many cancer cell lines." (PMID 38841361, 2024). "This provides an important reference for the prognostic monitoring of cancer, and also makes a potential contribution to the future research on cancer treatment targeting LDHA." (PMID 38709280, 2024).
cancer (continued). "Beyond traditional chemotherapy, cetuximab, an anti-EGFR monoclonal antibody, counteracts the Warburg effect by inhibiting HIF-1α regulated lactate dehydrogenase A (LDH-A), thus, disrupting the metabolic reprogramming that promotes cancer cell survival." (PMID 39169426, 2024). "Because activated lymphocytes also upregulate LDHA and engage in glycolysis in order to execute tumoricidal function, we compared LDHA expression levels in human lymphocytes to that of cancer types and corresponding normal tissue." (PMID 39225102, 2024). "We performed Cox correlation analysis to evaluate the relationship between LDHA expression levels and OS in various cancer types." (PMID 38198170, 2024). "Using the TISIDB database, the correlation of LDHA expression with molecular subtypes in different cancers was performed." (PMID 38291366, 2024). "High levels of LDHA assist in the formation and proliferation of cancer cells by promoting EMT, angiogenesis, cytoskeletal remodeling, increased cell viability, invasion and migration." (PMID 38163874, 2024). "In this study, we investigated the relationship between CNV of LDHA and patient survival across twenty-four different cancer types in TCGA." (PMID 38198170, 2024). "Collectively, these discoveries provide a solid basis for LDHA inhibitors targeting the process of lactylation in the treatment of cancer." (PMID 39502530, 2024). "For malignant cells, consistently upregulated metabolic genes were predominantly associated with cancer hallmark pathways, including glycolysis (GAPDH, GPI and LDHA), OXPHOS (COX6B1 and ATP5MC2), and nucleotide metabolism (TK1, GUK1, NME1)." (PMID 39393173, 2024). "Analyzing the expression of LDHs genes including LDHA, LDHB, LDHC and LDHD in all cancer types, we found that the expression of LDHA, LDHB and LDHD was higher than that of LDHC in pan-cancer." (PMID 38291366, 2024). "To further validate the role of LDHA in cancer immunotherapy, we conducted the following experiments in the realm of PC." (PMID 38664705, 2024). "The relationships between LDHA level and clinicopathologic features have been found in different cancers." (PMID 39582531, 2024). "In cancer cells, LDHA facilitates rapid conversion of pyruvate to lactic acid, minimizing pyruvate entry into TCA cycle in the mitochondria." (PMID 38163874, 2024). "LDHA catalyzed the conversion of pyruvate into lactate, maintaining an acidic microenvironment and contributing to cancer cell growth." (PMID 38474453, 2024). "Among them, LDHA plays a key role in the Warburg effect or aerobic glycolysis, which is commonly observed in cancer cells under hypoxic conditions." (PMID 39107908, 2024). "Cancer cells mainly consume glucose within the tumors, with LDHA being one of the key glycolysis-related enzymes." (PMID 39343933, 2024). "Subsequently, CRISPR screening identified LDHA as a pan-cancer biomarker for estimating immunotherapy response and survival probability which was further validated using immunohistochemistry (IHC) and spatial transcriptomics (ST) datasets." (PMID 38664705, 2024). "Due to the increased expression of LDHA in cancer and its primary role in lactate production position, LDHA is a potential candidate for cancer treatment." (PMID 39678492, 2024). "Preclinical data suggest that solute carrier family two facilitated glucose transporter member 1 (SLC2A1) and lactate dehydrogenase A (LDHA) are viable drug targets for cancer treatment." (PMID 38555429, 2024). "We therefore analyzed publicly available PDAC scRNA-seq data and observed elevated LDHA expression levels in cancer cells." (PMID 39343933, 2024). "LDHA seems to be a molecular target in various cancer therapies, but little is known about the function of LDHA in EC progression." (PMID 39582531, 2024). "Lactate dehydrogenase A (LDHA), a critical enzyme involved in glycolysis, is broadly involved multiple biological functions in human cancers." (PMID 38709280, 2024).
cancer (continued). "The increased expression of LDHA is regulated by many oncogenes, promoting glycolysis and malignant progression of cancers, which is mediated by ncRNAs." (PMID 38238756, 2024). "The previous results suggested LDHA expression is relevant to prognosis and immune cell infiltration in some human cancers." (PMID 38709280, 2024). "LDHA catalysed reactions primarily lead to the production of lactate, serving as the ultimate driver of the Warburg effect in cancer cells." (PMID 39021353, 2024). "In the healthy state, LDHA is prominently expressed in glycolytic cancer cells and PRs, where it converts pyruvate to lactate, the final step of aerobic glycolysis." (PMID 38773556, 2024). "LDHA is an important enzyme that promotes and maintains glycolysis, and the proliferation of cancer cells depends on its activity." (PMID 38715141, 2024). "LDHA is a key gene regulating the process of glycolysis, which is commonly upregulated in cancer tissues." (PMID 38990159, 2024). "This synergy suggests that LBP treatment triggers a feedback mechanism where increased LDHA expression helps cancer cells survive under the stress of chemotherapy by maintaining their glycolytic pathway, which is crucial for energy production." (PMID 39680520, 2024). "Our study highlights the impact of LDHA expression on different aspects of pan-cancer in humans, providing possible theoretical knowledge for the effective treatment of malignant tumors, and LDHA has the potential to be used as a marker for cancer therapy." (PMID 38709280, 2024). "Hypoxia has also been shown to promote L-2HG production via lactate dehydrogenase A, which maintains cancer stem cells and promotes immune evasion in PDAC." (PMID 39713022, 2024). "Next, we analyzed PDAC patients and divided them into two groups: LDHA-high and LDHA-low expression in cancer cells." (PMID 39343933, 2024). "LDHA is considered a key enzyme involved in cancer metabolism and can serve as a prognostic indicator." (PMID 38764020, 2024). "Inactivating SLC2A1 or LDHA affects the glycolytic pathway of cancer cells, ultimately leading to apoptosis in vitro and in vivo." (PMID 38555429, 2024). "Intriguingly, a previous study found that siRNAs specifically targeting LDHA demonstrated the inhibition of cancer progress, thereby showing a potential therapeutic strategy for LDHA-dependent malignancies." (PMID 39502530, 2024). "Using the cBioPortal database, we attempted to study the genetic alterations of LDHA in a wide range of cancers." (PMID 38709280, 2024). "The results showed that LDHA amplification patterns exhibited in most cancer types, particularly in UCEC." (PMID 38709280, 2024). "In recent years, with a deeper understanding of the metabolic characteristics of cancer cells, LDHA, a key enzyme in the glycolysis process, has garnered widespread attention from researchers." (PMID 39680520, 2024). "Additional IHC analyses of CRCLMs from both HGPs confirmed upregulation of lactate dehydrogenase A (LDHA) in cancer cells of predominantly rHGP CRCLM." (PMID 36691028, 2023). "LDHA knockdown reduced glycolysis and compromised proliferation in cancer cells and in mouse models." (PMID 36628612, 2023). "LDHA is an important enzyme in the glycolysis pathway that catalyzes the formation of lactate from pyruvate in the acidic microenvironment of cancer." (PMID 36937004, 2023). "HIF1A facilitates cancer development through the promotion of glycolysis via activation of LDHA, a key glycolysis-related enzyme, and the content of LDHA was markedly reduced by M4N+TMZ combination treatment." (PMID 37228120, 2023). "As a kind of lactate dehydrogenase enzyme, LDHA played a vital role in glucose metabolism and many signal pathways related to cancer development, and it has been regarded as a biomarker for prognosis of many cancers." (PMID 37925501, 2023).
cancer (continued). "Some miRNAs such as miR-34a and miR-30a-5p negatively regulate LDHA levels and inhibit glycolysis in cancer cells by targeting LDHA, resulting in decreased glucose uptake and lactate production." (PMID 37204526, 2023). "HIF1 is also involved in glucose metabolism in cancer and increases glycolysis by inducing transcription of the glucose-metabolism-associated genes, including GLUT, LDHA and monocarboxylate transporter 4 (MCT4), or inhibiting mitochondrial function." (PMID 37190158, 2023). "FoxM1 promotes glycolysis, proliferation, and migration of cancer cells through transcriptional regulation of LDHA." (PMID 36994237, 2023). "Further analysis revealed that co-culturing with cancer cells induced a major shift in CAF metabolism with increased expression of genes involved in glycolysis (SLC2A, GAPDH, LDHA, SLC16A3, ENO2, CA12), and the Hallmark gene set glycolysis." (PMID 37261365, 2023). "Further study revealed that LDHA expression in cancer tissues of patients with PC is higher than that in adjacent tissues, and patients with high LDHA expression have a worse prognosis than those with low expression." (PMID 36937004, 2023). "LDHA is the key enzyme involved in this process, where it converts pyruvate to lactate even in the presence of oxygen in cancer cells." (PMID 37892209, 2023). "Inhibition of LDHA activity or decreasing LDHA gene levels suppresses cancer cell growth both in vitro and in vivo." (PMID 36674619, 2023). "Several pharmacological inhibitors for LDHA have previously been reported for use in cancer, and there are currently several studies looking for more selective inhibitors." (PMID 37326348, 2023). "LDHA inhibitors presented as a promising therapeutic option, as blocking the function of LDHA leads to cancer cell apoptosis." (PMID 37480145, 2023). "Both desuccinylation by SIRT5 and succinylation by succinyl-transferase should be considered for the potential role of LDHA succinylation as a key regulator in promoting cancer progression." (PMID 35278714, 2023). "More importantly, much higher LDHA abundance was observed in the nuclear space of the cancer tissues than in that of the normal tissues." (PMID 37779146, 2023). "Elevated LDHA expression was found in cancer cells and tissues and related to worse prognosis in cancer patients." (PMID 37770937, 2023). "A study found that oxaloacetate (OAA) inhibits human lactate dehydrogenase A (LDHA) in cancer cells, reversing the Warburg effect." (PMID 38106701, 2023). "Medicinal plants can unleash new avenues for discovering new effective inhibitors with insignificant side effects that can exert anti-cancer potential targeting LDHA." (PMID 36583135, 2023). "We found that lactate dehydrogenase A (LDHA) regulated pyruvate metabolism and was significantly associated with the development of cancer, while the eQTL and pQTL of LDHA in blood were also available in publicly available databases." (PMID 37132247, 2023). "The correlation between increased LDHA expression and cancer progression suggests that LDH activity is an important factor to consider for cancer treatment." (PMID 35278714, 2023). "In this process, lactate dehydrogenase A (LDHA) acts as a key player, and it is found that cancer cells induce LDHA activity via the persulfidation of LDHA at Cys163." (PMID 37627515, 2023). "LDHA is an important energy-metabolizing enzyme with elevated expression in most cancer cells compared to normal tissues." (PMID 36447119, 2023). "Studies have shown that serum lactate levels and tumoural expression of lactate dehydrogenase A and B have prognostic value in several cancer types." (PMID 35708739, 2023). "Consistent with metabolite profiling, IHC revealed that LDHA, as an enzyme regulating glycolytic metabolism, was highly expressed in the cancer region, while it was significantly decreased in the Akk gavaged group." (PMID 36740846, 2023).
cancer (continued). "SCIC2.1 downregulates the expression of LDHA and reduces lactate production, suggesting its promising anti-cancer activity." (PMID 37715252, 2023). "Berberine is known to exhibit anti-cancer activity through inhibition of LDHA activity and reduction of lactate production in cancer cells." (PMID 37915411, 2023). "One of the key changes in the reprogramming of energy metabolism in cancer cells is an increase in glucose uptake and its conversion to lactate by the enzyme lactate dehydrogenase A (LDHA)." (PMID 37624791, 2023). "LDHA is upregulated in many cancers, including GBM, and inhibition of LDHA can halt growth and induce differentiation and apoptosis among A172, U87, and U251 GBM cells and GBM stem cells." (PMID 37107600, 2023). "Hypoxia induced abnormal activation of hypoxia-inducible factor-1α (HIF-1α) in the immune microenvironment, and also upregulated LDHA and GLUT1 to cause glycolysis, which promoted the progression of HCC and led to enhanced drug resistance of cancer cells." (PMID 37663261, 2023). "Similar to cancer cells, photoreceptor cells produce lactate aerobically through lactate dehydrogenase A (LDHA), which converts pyruvate to lactate and utilizes NADH as a cofactor." (PMID 36896135, 2023). "This study illustrated that heightened LDHA expression resulted in amplified glucose uptake and lactate production within cancer cells." (PMID 38248716, 2023). "Most PDAC tumors are driven by aberrant KRAS activity, and a line of evidence suggests that oncogenic KRAS signaling enhances glycolysis in cancer cells by increasing the expression of glycolytic enzymes, such as lactate dehydrogenase A (LDHA)." (PMID 37733442, 2023). "Lactate Dehydrogenase A (LDHA) enzyme is considered as a key player in cancer progression and is targeted frequently to develop anticancer medications." (PMID 36583135, 2023). "Lactate dehydrogenase (LDHA) is a key enzyme in the glycolytic process, and the acidic environment established by glycolysis contributes to the immune escape of cancer cells." (PMID 36894874, 2023). "Inhibition of LDHA reduces proliferation, migration, invasion, angiogenesis and cancer metastasis of various cancer cells." (PMID 37853052, 2023). "Immunohistochemistry analysis was conducted to measure GLUT3, LDHA, and L-lactyl levels in gastric normal and cancer tissues." (PMID 38041125, 2023). "Cancer cells use lactate dehydrogenase A (LDHA) to increase the rate of glycolysis to carry out an endless program of cell proliferation." (PMID 37895865, 2023). "Nonetheless, only a limited number of studies have assessed alterations in immune cell reactions towards LDHA inhibitors during cancer treatment." (PMID 37965333, 2023). "In fact, previous studies have highlighted the dispensability of the Warburg effect in cancer cell growth and have shown that a complete disruption of glycolysis would require the deletion of both LDHA and LDHB genes." (PMID 36768924, 2023). "Some specific LDHA inhibitors, such as FX-11 (a benzoxazole-based inhibitor) and Compound 3a (a quinoline-based inhibitor), have shown selective inhibition of cancer cell growth." (PMID 37915411, 2023). "Quercetin, found in several foods, including apples and onions, reduces LDHA activity and triggers apoptosis in cancer cells, effectively inhibiting cellular glycolysis by reducing LDHA expression, thereby suppressing lactic acid generation and glucose uptake." (PMID 37915411, 2023). "It is therefore vital that circRNA regulates LDHA expression or activity because this mechanism not only influences the development of tumors but also the therapy of malignant carcinomas." (PMID 36628612, 2023). "Some of these proteins, specifically RhoA, Vimentin, LDHA and are very important proteins in the development and progression of cancer." (PMID 36313672, 2022). "Differences in posttranslational modifications have been suggested to regulate the enzymatic activity of LDHA in human cancers." (PMID 35525866, 2022).